FZD7 (frizzled class receptor 7)
Diseases named in the same sentence as FZD7 in open-access papers (continued):
Sharing a sentence is not in itself a finding about the gene and the disease.
cancer (continued). "In a recent study, Kalhor and colleagues assessed the three-dimensional structure of human Wnt2-Fzd7 CRD complex via bioinformatics approaches, and the data demonstrated a unique dynamic behavior of Wnt2 upon binding to Fzd7, which is highly useful in targeted therapy for Wnt2-related cancers." (PMID 32923386, 2020). "FZD7 contributes to cell stemness in several normal and cancer cells." (PMID 30548372, 2019). "Small molecules that act as classic GPCR modulators targeting Fzd7 to regulate WNT/β‐catenin signaling may therefore represent potential cancer therapeutics." (PMID 30259711, 2018). "The identified small molecular Fzd7 inhibitors can serve as a useful tool for studying the regulation mechanism(s) of Wnt/Fzd7 signaling as well as a starting point for the development of cancer therapeutic agents." (PMID 29207657, 2017). "In addition, various studies have shown that targeted inhibition of FZD7 displays anti-cancer activity in vitro and in vivo." (PMID 27852064, 2016). "FZD7 plays an important role in stem cell biology and cancer development and progression." (PMID 27852064, 2016). "Wnt signalling is also deregulated in lung cancer and prostate cancer, but it is unknown if FZD7 is important in these two devastating cancers with very high morbidity rates." (PMID 27196929, 2016). "Developmental pathways are often deregulated in cancers, and thus it is tempting to speculate whether FZD7 may be involved in hematopoietic malignancies as T-cell maturation in the thymus is blocked by expression of the FZD7 ectodomain." (PMID 27196929, 2016). "Activation in the Wnt/β-catenin pathway through FZD7 may carry specific implications in the context of cancer stemness." (PMID 27105493, 2016). "Fzd7 is of particular interest as it is the Wnt receptor most commonly up-regulated in several different cancers and can also transmit signals through the different arms of the Wnt pathway referred to broadly as canonical (Wnt/β-catenin dependent) and non-canonical (Wnt/β-catenin independent)." (PMID 27196929, 2016). "Therefore, targeted inhibition of FZD7 represents a rational and promising new approach for cancer therapy." (PMID 25313882, 2014). "The over-activation of Wnt signaling with the up-regulated expression of FZD7 in various types of cancer and the roles of FZD7 in cancer stem cell biology suggest that FZD7 might serve as a therapeutic target for certain cancers." (PMID 25313882, 2014). "Furthermore, Frizzled type 7 receptor (FZD7), the most important Wnt receptor involved in cancer development and progression, was identified as a functional target of miR-199a." (PMID 25313882, 2014). "These progenitor cells possess many of the characteristics that cancer cells acquire as disease progresses, suggesting FZD7-mediated Wnt signaling may have a role in the transition of normal differentiated cells to more plastic phenotypes." (PMID 24897117, 2014). "Thus, targeted inhibition of FZD7 has been considered as a promising approach for cancer therapy." (PMID 36620565, 2022). "Moreover, pharmacological inhibition of SIRT1/2 interferes with the Wnt pathway by decreasing the expression of Dishevelled proteins, frizzled 7 receptor (FZD7) and beta-catenin in various cancer cells, which ultimately leads to inhibition of cell growth and cell migration." (PMID 25915617, 2015). "Given the emerging interest in peptide-based cancer therapeutics, and recent advances in improving peptide stability and delivery, we propose that the sFZD7 peptide is a feasible therapeutic agent that can be used to specifically abolish the functional activity of FZD7 in HCC." (PMID 21314951, 2011). "Small interfering RNAs (siRNAs) have downregulated overexpressed FZD receptors, such as FZD7 and FZD10, in cancers like colorectal and liver carcinomas." (PMID 40376615, 2025). "YBX1 is a well-established transcription factor that has been reported to induce the transcription of oncogenic genes, such as FOXA1, FZD7, and HOXC8 in cancers." (PMID 38491348, 2024).
cancer (continued). "Frizzled family receptor 7 (FZD7) is a Wnt signaling receptor, which is involved in the maintenance of cancer cell stemness and cancer progression." (PMID 35784328, 2022). "While positive staining for WNT7B was observed obviously in the cytoplasm of the majority of malignant tissues, WNT5A, FZD7 and GPC1 signals were presented on both the cytoplasm and membrane of cancer cells." (PMID 35850748, 2022). "Accordingly, targeted inhibition of Fzd7 exhibits a promising therapeutic option for GC and CRC cancers." (PMID 35655594, 2022). "Members in FZD family including FZD2, FZD4, FZD7, FZD8 and FZD10 have been demonstrated to mediate cancer cell epithelial-mesenchymal transition (EMT)." (PMID 33618713, 2021). "FZD7 is a TCF/β-catenin target gene and forms a positive feedback loop in various cancers, including HCC." (PMID 32486480, 2020). "Our study led to the identification of an Fzd7 inhibitor, SRI37892, with potent activities against Wnt/β-catenin signaling and cancer cell viability." (PMID 29207657, 2017). "The best hit, SRI37892, significantly blocked the Wnt/Fzd7 signaling with IC50 values in the sub-micromolar range and inhibited cancer cell proliferation with IC50 values around 2 μM." (PMID 29207657, 2017). "It has been reported that FZD7 is upregulated in TNBC, and that FZD7 plays an important role on Wnt/β-catenin signaling in TNBC cells and cancer cell proliferation." (PMID 29207657, 2017). "One of the targets of hsa-mir-199a/b is FZD7, the most important WNT receptor in cancer development and progression." (PMID 27806083, 2016). "Recent studies have identified the Frizzled-7 receptor (FZD7), important for activation of Wnt-mediated signaling, as a potential therapeutic target for HCC and other cancers." (PMID 21314951, 2011). "Similarly, several effector molecules, including CALD1, CDH1, FN1, FZD7, RAC1, STAT3, and WNT11, were downregulated in cancer cells treated with DBMSCs." (PMID 39768220, 2024). "Frizzled-7 (FZD7), a key receptor for Wnt/-catenin signaling, is overexpressed in TNBC, suggesting that it could be a viable target for cancer therapy." (PMID 36276155, 2022). "PIK3CA-mutant cancers displayed higher expression of 12 of the 17 Wnt genes compared to PIK3CA wild-type tumors, including five Wnt target genes (LEF1, MYCN, FZD7, SFRP2, and TNFRSF11B) and seven Wnt signaling components (TCF7L1, TCF7L2, CTNNB1, FZD4, SFRP1, WNT5A, and MSX2)." (PMID 34035258, 2021). "FZD7 mRNA levels were also increased; overexpression of different Frizzled (FZD) receptors have been also reported to over-activate the Wnt signaling pathway in a variety of cancers." (PMID 31671889, 2019). "Besides blocking the interaction between FZD7 and DVL to target cancer, Wnt signaling can also be inhibited through the blockade between Wnts and FZD receptors." (PMID 29361730, 2018). "As both the canonical and non-canonical pathways are deregulated in many different cancers, Fzd7 offers an exciting target for therapeutic intervention and will be the main focus of this review." (PMID 27196929, 2016). "Moreover, genes in the WNT, SHH, and BMP pathways such as WNT5A, FZD7, and FZD5, SHH, SMO, and GLI2 as well as BMP4 were likewise among the upregulated genes and were included in pathway of cancer gene set." (PMID 26998479, 2015). "Fzd7 inhibitors, monoclonal antibodies against ROR2, and small-molecule inhibitors of EV biogenesis or uptake are under active investigation in several cancers and may offer combinatory strategies with androgen deprivation and/or chemotherapy to mitigate EV-mediated pro-metastatic signalling." (PMID 41007281, 2025). "Additionally, elevated FZD7 mRNA levels have been reported in HCC and other cancers." (PMID 21314951, 2011). "Wnt5a, a representative Wnt ligand of the non-canonical pathway and FZD7, a receptor for secreted WNT proteins, promote cancer cell metastasis, EMT and chemoresistance in several cancers." (PMID 31671889, 2019).
cancer (continued). "WNT5A, a secreted signaling protein involved in canonical and non-canonical WNT signaling, and FZD7, a receptor for WNT5A and other WNT proteins, are both overexpressed in numerous cancers where they contribute to the EMT phenotype." (PMID 27574697, 2016). "The expression was not interrelated (i.e., between LGR5, FZD7, and MIST1) and may reflect the coexistence of different CSC phenotypes supporting the contention that cancers can harbor heterogeneous and biologically distinct populations of CSCs." (PMID 31827644, 2019).
infection (3 papers, 2009 to 2021). The state of being infected such as from the introduction of a foreign agent such as serum, vaccine, antigenic substance or organism. "miR-34a KO and miR-34a/b/c KO organoids also showed increased expression of Lrp6 and Fzd7, similar to the Wnt-independent organoids generated upon infection." (PMID 33579932, 2021). "Live imaging was performed on the chick metacarpals expressing H2B-GFP (green), mCherry (red) and Fzd7-ΔPDB via RCAS infection (a)." (PMID 28994649, 2017). "Since the duration of siRNA-mediated repression might not be sufficient for the 6-day study time course, stable repression of FZD5 and FZD7 was sought using lentiviral shRNA infection of targeted cells." (PMID 19874621, 2009). "(e–g) In the chick metacarpals expressing Ncad-GFP (green) via RCAS infection, live imaging revealed that the fusion protein was enriched in the interface of sister cells in wild-type tissues (e) (n = 6) and tissues coexpressing Fzd7-ΔPDB (n = 6) over time (f)." (PMID 28994649, 2017).
adenocarcinoma (1 paper, 2023). A common cancer characterized by the presence of malignant glandular cells. "We also postulated that Fzd7 deletion indirectly initiates tumorigenesis in the intestines, and our results show that Fzd7 deficiency (intrinsic defect) combined with DSS treatment (extrinsic factor) can induce adenocarcinoma in mice." (PMID 36691900, 2023).
FZD7 also shares sentences with these, for which no sentence is quoted: gastrointestinal tumors (2 papers); intracerebral hemorrhage (2); ischemia (2); ischemic cardiomyopathy (2); keloid (2); oral squamous cell carcinoma (2); renal carcinoma (2); atherosclerosis (1); bladder (1); brain cancer (1); cardiovascular disease (1); cerebral infarction (1); cholangiocarcinoma (1); colorectal tumor (1); depression (1); dilated cardiomyopathy (1); encephalitis (1); endometrium cancer (1); head and neck cancer (1); head and neck squamous cell carcinoma (1); heart failure (1); hematologic malignancies (1); hemorrhage (1); idiopathic cardiomyopathy (1); invasive breast carcinoma (1); leiomyoma (1); lip (1); liver steatosis (1); lung adenocarcinoma (1); mantle cell lymphoma (1).
A further 9 diseases each share a sentence with FZD7 in 1 paper.